ARHGAP19 (Rho GTPase activating protein 19)
Description:
Has GTPase activator activity toward RHOA; RHOA activation results in GTP hydrolysis and conversion from an active GTP-bound to an inactive GDP-bound state. Lacks GTPase activator activity toward RAC1 or CDC42.
Synonyms: FLJ00194; MGC14258; CMT2KK
Tractability: Antibody: its Gene Ontology location is reachable by antibodies, with high confidence; the Human Protein Atlas places it where antibodies can reach. PROTAC: ubiquitination databases record sites on it.
Gene: Protein-coding gene on chromosome 10 (97,222,173 to 97,292,673, reverse strand). Ensembl gene ENSG00000213390.
Subcellular location: Nucleus; Cytoplasm; Cytoplasm, cell cortex
Subcellular location (Human Protein Atlas): Plasma membrane
Pathways (Reactome):
Signal Transduction: RHOA GTPase cycle
Gene Ontology:
Molecular function: GTPase activator activity; GTPase binding; protein binding
Biological process: regulation of small GTPase mediated signal transduction; signal transduction
Cellular component: cytoplasm; equatorial cell cortex; nucleus; plasma membrane; cytosol; cell cortex
Genetic constraint (gnomAD): Loss-of-function variants: 38 observed, 48.68 expected, observed/expected ratio (o/e) 0.78, 90% interval 0.6 to 1.02. The upper end of that interval is the gene's LOEUF score, 1.02, which puts it in group 4 of 6, group 1 being the genes least tolerant of losing a copy. Missense variants: 489 observed, 552.58 expected, observed/expected ratio (o/e) 0.88, 90% interval 0.82 to 0.95. Synonymous variants: 186 observed, 202.77 expected, observed/expected ratio (o/e) 0.92, 90% interval 0.81 to 1.04.
Homologues: Orthologues: chimpanzee ARHGAP19 (96% identical), dog ARHGAP19 (95% identical), macaque ARHGAP19 (95% identical), rabbit ARHGAP19 (93% identical), pig ARHGAP19 (92% identical), mouse Arhgap19 (88% identical), guinea pig ARHGAP19 (85% identical), rat Arhgap19 (84% identical), tropical clawed frog arhgap19 (67% identical), zebrafish arhgap19 (56% identical), Drosophila melanogaster RhoGAP54D (29% identical). Paralogues in human: ARHGAP18 (22% identical), ARHGAP40 (21% identical), ARHGAP28 (18% identical).
Diseases named in the same sentence as ARHGAP19 in open-access papers:
ARHGAP19 is named in the same sentence as 7 diseases in open-access papers, as found by Europe PMC text mining. Sharing a sentence is not in itself a finding about the gene and the disease. The quoted sentences say what the papers report.
lung carcinoma (2 papers, 2012 to 2024). "By applying screening criteria of rec = 5 in the lung cancer group and rec = 9 in the nodule group, while excluding the control group, a total of 2 mutation events (ARHGAP19 and NRG1) were identified." (PMID 39389944, 2024). "Interestingly, in relation to clinical pathological parameters of Asian lung cancer patients, mRNA overexpression of ARHGAP19 and FRAT2 was significantly associated with lung SCC." (PMID 22691236, 2012). "The mean gene dosage of lung cancer candidate genes ARHGAP19, FRAT2, PAFAH1B1, and ZNF322A in tumor tissues was significantly higher than the corresponding normal tissues in Asian lung cancer." (PMID 22691236, 2012). "CISH analysis of patients indicated that copy number amplification indeed occurred for ARHGAP19 and ZNF322A genes in lung cancer patients." (PMID 22691236, 2012). "In addition, CISH analysis of patients indicated that copy number amplification indeed occurred for ARHGAP19 and ZNF322A genes in lung cancer patients." (PMID 22691236, 2012).
epithelial ovarian cancer (1 paper, 2013). "miR-193a induced the inhibition of DNA synthesis and apoptosis by targeting genes including ARHGAP19, CCND1, ERBB4, KRAS, MCL1, indicating a tumor suppressive role of this miRNA in epithelial ovarian cancer cells." (PMID 23588298, 2013).
neuropathy (1 paper, 2025). A disorder affecting the nervous system that manifests with pain, tingling, numbness, and/or muscle weakness. "Here, we identified 16 recessive variants in the RhoGTPase activating protein 19 gene (ARHGAP19) causing motor-predominant neuropathy in 25 individuals from 20 unrelated families." (PMID 41086021, 2025). "We provide clinical, genetic and functional evidence that implicate ARHGAP19 as a novel causative gene for inherited neuropathy." (PMID 41086021, 2025).
tumor (4 papers, 2012 to 2021). "Moreover, a well-described tumor suppressor miR-200c targets TUBB3, MSN, and ARHGAP19, which regulate multiple cytoskeletal-related events." (PMID 34298609, 2021).
cancer (2 papers, 2011 to 2015). A tumor composed of atypical neoplastic, often pleomorphic cells that invade other tissues. "Some of the other identified targets of miR-200c include Moesin (MSN), Fibronectin 1 (FN1), and Rho GTPase activating protein 19 (ARHGAP19), important regulators of the migratory and invasive capacity of cancer cells." (PMID 26283969, 2015). "ARHGAP19 is a member of a family of GTPase activating proteins, and other family members, 8, 9, 12 and 15, are expressed in several types of cancer and activate Cdc42, Rac1 or RhoA, small GTPases required for migration." (PMID 21501518, 2011).
ARHGAP19 also shares sentences with these, for which no sentence is quoted: endometrial cancer (1 paper); hepatocellular carcinoma (1).